LGALS8 (galectin 8)
Diseases named in the same sentence as LGALS8 in open-access papers (continued):
Sharing a sentence is not in itself a finding about the gene and the disease.
tumor (69 papers, 2010 to 2026). "One of the emerging factors implicated in tumor progression and resistance is galectin-8, a member of the galectin family of β-galactoside-binding proteins." (PMID 39895791, 2025). "Galectin-8-linked tumor invasion and metastatic tumor cell spread are also regulated by immunomodulatory cytokines and chemokines." (PMID 36873388, 2023). "Galectin-8 (Gal-8), another tandem-repeat type of galectins, has been suggested to be associated with tumor cell adhesion, tumor cell survival, and metastasis." (PMID 36232695, 2022). "A combination of Otud6b, Stk39 and Lgals8 gave an AUC of 0.868 (95% CI 0.744-0.968, p < 0.001) for pre-diagnostic sera and 0.871 for sera derived from tumor bearing mice (95% CI 0.744-0.976, p < 0.001) with a sensitivity of 0.75 and specificity of 0.8." (PMID 24886063, 2014). "Indeed, galectin-8 is strongly implicated in cell adhesion, growth and cytoskeletal organization, thus underlining a possible favorable function in tumor development and progression." (PMID 35682991, 2022). "Finally, the loss of galectin-8 in bladder tumours increases tumour recurrence, while decreased immunohistochemical staining is associated with higher tumour stage and grade." (PMID 29207682, 2017). "Studies have shown that higher intratumoral expression of galectin-8 is significantly correlated with smaller tumor size, reduced recurrence rates, and improved overall survival." (PMID 40710343, 2025). "These interconnections indicate that galectin-8 plays a central role in linking processes that drive tumor invasiveness, suppress the immune response, and enable cancer cells to resist treatments." (PMID 39895791, 2025). "Studies have revealed that galectin-8 plays a crucial role in promoting tumor growth and metastasis by modulating the tumor microenvironment." (PMID 39895791, 2025). "Further supporting the role of galectin-8 in tumor progression, knockdown of galectin-8 also significantly reduced cell migration, as evidenced by both Transwell and IncuCyte assays." (PMID 39895791, 2025). "Prior studies have linked several genes (LGALS8, PTPN12, YTHDC2, APOBEC3G, GPX3, RASA3, and TSPAN4) to immune responses, highlighting the impact of the tumor microenvironment (TME) on DCIS." (PMID 41020869, 2025). "Galectin-8 (Gal-8) is a multifunctional lectin involved in cell adhesion, immune regulation, and intracellular signaling, exhibiting both tumor-promoting and tumor-suppressive properties depending on context." (PMID 40710343, 2025). "The enrichment of basal subtype characteristics in the high galectin-8 expression group underscores the importance of galectin-8 in driving aggressive tumor behaviors." (PMID 39895791, 2025). "Galectin-8 seems to be a modulator of tumor development and progression, being able to suppress or promote tumor growth." (PMID 39000016, 2024). "With regard to tumor angiogenesis, it has been described that elevated galectin-8 serum levels, which were observed in breast and colorectal cancer, can stimulate endothelial cell tube formation." (PMID 38990363, 2024). "Together, these results show that the increased expression of galectin-8 in mice transplanted with CRC cells effectively reduced tumor growth and liver metastasis." (PMID 39231945, 2024). "Galectin-8 secreted by tumor cells was also found to induce vascular permeabilization, one of the first steps in the endothelial response to pro-angiogenic stimulation." (PMID 38990363, 2024). "Results from immunohistochemistry (IHC) staining with clinical CRC samples showed that galectin-8 expression is downregulated during CRC tumor progression, with a significant difference between stages T1 and T4." (PMID 39231945, 2024). "Galectin-8 can enhance tumor metastasis by regulating the rearrangement of the cytoskeleton and E cadherin expression, inhibiting anoikis and homotypic aggregation of cancer cells." (PMID 36873388, 2023).
tumor (continued). "Currently, few studies have evaluated the effect of galectin-8 in the process of anti-tumor immune activation." (PMID 34572756, 2021). "Galectin-8 is a carbohydrate-bindingprotein that plays a crucialrole in tumor progression and metastasis, antibacterial autophagy,modulation of the immune system, and bone remodeling." (PMID 34795863, 2021). "They observed an increase in cell growth of the U87 cell line when recombinant galectin-8 was added to tumor cell cultures and verified changes in cell proliferation when this tandem-repeat lectin was downregulated in this cell line." (PMID 35008740, 2021). "This study investigates the prognostic influence of the expression of galectin-7 (Gal-7) and galectin-8 (Gal-8) in tumor cell cytoplasm, nucleus and on surrounding immune cells." (PMID 32290551, 2020). "Taken together, our data reveal the existence of a previously uncharacterized clathrin-independent endocytic process controlled by galectin-8 and endoA3, essential for the downmodulation of the tumor marker CD166 at the cell surface." (PMID 32193381, 2020). "Distances between tumor cells (positivity for galectin-8 at high intensity) and lymphocytes as well as between galectin-1-positive tumor cells were of prognostic relevance in testicular cancer patients with lung metastases." (PMID 24443956, 2014). "Galectin-8 (Gal-8), one of the most widely expressed galectins, is involved in tumour progression and modulation of immune responses." (PMID 26082317, 2013). "Other family members, including Galectin-7 and Galectin-8, display context-dependent functions that may either promote or inhibit tumor development." (PMID 42129932, 2026). "In addition, we found that reducing galectin-8 expression in drug-resistant cell lines not only reinstated the effectiveness of anticancer drugs but also suppressed tumor cell proliferation and migration." (PMID 39895791, 2025). "The anti-malignant effects of galectin-8 in the tumor microenvironment might also be related to its anti-inflammatory properties and its regulation of T cell homeostasis." (PMID 39231945, 2024). "Furthermore, inducible expression of galectin-8 attenuated tumor development and metastasis of CRC cells in an intra-splenic injection model." (PMID 39231945, 2024). "LGALS8 was found to be expressed almost equally in both tumor and normal tissues." (PMID 38544823, 2024). "At the same time, galectin-8 could then suppress cell migratory activity of B4GALT1-expressing CRC cells to reduce tumor progression." (PMID 39231945, 2024). "Thus, similar to galectin-1 and galectin-3, current findings suggests that galectin-8 can stimulate endothelial cell functions but identifying the exact role of the protein in tumor angiogenesis requires further investigation." (PMID 38990363, 2024). "Additionally, we found that the expression of galectin-8, detected by IHC, in the metastatic nodules of all groups was lower than in the primary tumor tissues in the spleen." (PMID 39231945, 2024). "It is, therefore, logical to raise the hypothesis that galectin-8 can act as a tumor suppressor via its “GALTOR”-like activity, a term used by Jia and collaborators to define a dynamic galectin-based regulatory subsystem controlling mTOR." (PMID 37753083, 2023). "Galectin-8 is currently limited in pancreatic cancer, but in other solid cancers, it exhibits potent pro-inflammatory effects, suppresses immune cell function in tumor cells, and promotes tumorigenesis." (PMID 36428567, 2022). "Interestingly the selective knockdown of galectin-8 in a mouse model showed a notable reduction of the tumor size and a minor metastatic process, highlighting its importance as potential therapeutical target." (PMID 35682991, 2022). "On the contrary, galectin-8-based strategies could potentiate anti-tumor immunity since this lectin can lower the TCR activation threshold." (PMID 34572756, 2021).
tumor (continued). "In their results, they demonstrated that soluble galectin-8 increased migration of U87 cell lines in a transwell assay, although silencing galectin-8 did not affect the promigratory capacity of these cells, but clearly influenced tumor cell proliferation." (PMID 35008740, 2021). "Galectin-8 and galectin-9 both have two carbohydrate recognition domains and are tandem repeat galactosins that regulate a variety of biological functions, including cell aggregation, cell adhesion, and tumor cell apoptosis." (PMID 34093804, 2021). "In addition, the expression of galectin-8 in solid tumors has also been proved to be closely related to tumor cell adhesion or metastasis." (PMID 34093804, 2021). "Inhibiting Galectin-8 itself or its binding to K-Ras and, thus, impeding K-Ras signaling might represent a new strategy to block tumor cell proliferation and motility and probably metastatic dissemination." (PMID 31861875, 2019). "The inhibition of Galectin-8 and, hence, interference with K-Ras signaling, may represent a new strategy for blocking tumor metastasis, since Galectin-8 is abundantly expressed in carcinoma." (PMID 31861875, 2019). "Inhibiting Galectin-8 and, hence, interfering with K-Ras signaling, might represent a new strategy to block tumor cell proliferation and motility and probably metastatic dissemination." (PMID 31861875, 2019). "IgM responses were found in 0% (Pdhx, Lgals8) to 20% (Stk39) of tumor bearing mice." (PMID 24886063, 2014). "In tumor bearing mice, IgG autoantibody incidence ranged from 5% (Pdhx, Stk39) to 50% (Lgals8)." (PMID 24886063, 2014). "Therefore, we particularly focused on sunitinib resistance and performed immunohistochemical experiments on tumor samples to validate the discriminatory potential of four new candidate biomarkers, LGALS8, RAB17, EpCAM, and CD9." (PMID 23555683, 2013). "The more aggressive the tumor, the less galectin-8 it harbored." (PMID 23658855, 2010). "Therefore, the available data point towards an organ and tumor-specific function of Galectin-8." (PMID 31861875, 2019). "Here, the authors show that the tumor marker CD166 is a clathrin-independent cargo that is taken up by endophilin-A3 and galectin-8, which regulates cancer cell migration." (PMID 32193381, 2020). "Finally, luciferase assays demonstrated that miR-7 significantly inhibits the activity of the 3′UTR of LGALS8, supporting a novel mechanistic link between miR-7 activity and impaired ECM-mediated tumor progression." (PMID 40813676, 2025). "While this was not further affected by tumor-derived conditioned medium, we did observe an additional reduction in cell surface galectin-8 on endothelial cells after conditioned medium treatment." (PMID 38990363, 2024). "Currently, there are no studies evaluating the impact of tumor galectin-8 on the generation of specific and protective immune responses." (PMID 34572756, 2021). "The expression of galectin-8 did not correlate with stage (P=0.303), lymph node involvement (P=0.326), tumor grade (P=0.769), distant metastasis (P=0.748), and age (P=0.574)." (PMID 33936231, 2021). "Autoantibodies specific for Lgals8 and Znf238 were discovered in mice that did not develop tumor during the time course of the study." (PMID 24886063, 2014). "Furthermore, although podoplanin has been implicated in pathological lymphangiogenesis via interaction with galectin-8, we found no obvious effects on tumor-induced LN lymphangiogenesis in mice lacking lymphatic podoplanin expression." (PMID 35892863, 2022). "Importantly, inhibition of LGALS8 expression may occur throught a direct posttranscriptional targeting by miR-7, establishing a mechanistic link between miR-7 activity and the suppression of ECM-driven tumor progression." (PMID 40813676, 2025). "Therefore, galectin-8 produced by non-CRC cells may also contribute to the regulation of tumor progression in vivo." (PMID 39231945, 2024).
cancer (48 papers, 2011 to 2025). A tumor composed of atypical neoplastic, often pleomorphic cells that invade other tissues. "While previous studies have implicated galectins, particularly Galectin-3, in cancer progression and resistance 27, our findings highlight the specific role of galectin-8 in Tarceva-resistant TNBC cells." (PMID 39895791, 2025). "Because inflammation increases the risk of developing many types of cancer, the anti-inflammatory properties of galectin-8 could contribute to the anti-malignant effect observed in vivo." (PMID 39231945, 2024). "Usually, they are located in the nucleus, but in cancer cells, Galectin-8 and -9 can be shifted to the cytoplasm, which we can confirm by a detected expression in both, the nucleus and cytoplasm." (PMID 39000016, 2024). "Our results suggest a correlation of high Galectin-8 expression with low grading and better survival rates, which match the already described pro-apoptotic effects of Galectin-8 and its effects in other cancers." (PMID 39000016, 2024). "In summary, little is known about the biological functions of galectin-8 in lymph nodes during cancer." (PMID 34572756, 2021). "Cell lysate fractionation analyses, as shown for PANC-1 cells in this study and several other carcinoma cell lines, revealed that Galectin-8 is localized in the cytosolic and membrane-containing fraction and it co-localizes with K-Ras at the plasma membrane." (PMID 31861875, 2019). "Galectin-1 has been found to be more effective on various carcinomas including epithelial tumors, galectin-7 on thyroid tumors, galectin-8 on colon cancer, and galectin-12 on fibroblast cells." (PMID 25730388, 2015). "Galectin-8 promotes cell adhesion by binding cell surface integrins, and its levels have been correlated with cancer progression." (PMID 21765917, 2011). "In contrast to other galectins, such as Galectin-3, which have been studied in the context of various cancer subtypes, our findings underscore the unique importance of galectin-8 in regulating drug resistance mechanisms through its influence on cell survival pathways​ 27, 30-32." (PMID 39895791, 2025). "Our goal was to evaluate whether decreasing galectin-8 expression could suppress the proliferation of these resistant cancer cells and restore their sensitivity to Tarceva treatment." (PMID 39895791, 2025). "It was suggested that galectin-8 functions in a fine balancing act between its effects on the expression of cytokines/chemokines, which promote cancer growth, and cytokine-mediated immune responses, which suppress cancer progression." (PMID 39337581, 2024). "A good example is the expression of galectin-1 and galectin-8 in cancer cells." (PMID 37753083, 2023). "As in the case of other galectins, however, galectin-8 may have a dual role depending on the cancer subtype or its intracellular localization." (PMID 37753083, 2023). "First, galectin-8 enhances (co-stimulates) early T responses in the lymph nodes, especially when the stimulus is limited or when the available T cell repertoire has low avidity for epitopes (cancer is such a case)." (PMID 34572756, 2021). "Galectin-8 has relationships with cell growth and metastasis of some cancers." (PMID 33936231, 2021). "However, more experimental data are needed to clarify these biological effects of galectin-8 in cancer." (PMID 34572756, 2021). "Galectin-8 (Gal-8) plays a significant role in normal immunological function as well as in cancer." (PMID 27973456, 2016). "Galectin-8 (Gal-8), a carbohydrate-binding protein that promotes cell proliferation by transactivating the EGFR-ERK signaling pathway, is overexpressed in several cancers." (PMID 40209344, 2025).
cancer (continued). "Genes LGALS8, PDE4DIP, RAD17, ELN, MUC4 and SEMA4D had a mid-range expression in both cancer types, while OPRM1 and ADRA1 were the least expressed, thereby corroborating the results from our box plot and survival analysis." (PMID 38544823, 2024). "Whether intracellular galectin-8 controls cancer progression is not clear yet, but the fact that it controls key signaling pathways suggests that it may be the case in several types of cancer." (PMID 37753083, 2023). "No significant changes in galectin-8 were observed in cancer relative to healthy controls." (PMID 34638303, 2021). "Finally, a decrease in galectin-8 in carcinomas, but not IPs, was shown." (PMID 24859692, 2014). "After the analysis of fold changes, upregulation in the mRNA level of LGALS1, LGALS3, LGALS4, LGALS8, and LGALS9 was detected in cancer patients compared to normal ovarian tissue." (PMID 36050693, 2022).
infection (28 papers, 2014 to 2026). The state of being infected such as from the introduction of a foreign agent such as serum, vaccine, antigenic substance or organism. "Galectin-8 (encoded by LGALS8) senses membrane damage induced by infection, both bacterial and viral, and subsequently targets the pathogens for autophagy." (PMID 34531865, 2021). "As less galectin-8 accumulated around damaged lysosomes following the infection of cells with vacuolating cytotoxin A (VacA)-deficient H. pylori, we concluded that VacA of H. pylori contributed to lysosomal damage and galectin-8 accumulation." (PMID 33663512, 2021). "In studies of bacteria-containing vacuoles a lysenin probe indicating sphingomyelin exposure generates continuous uniform labelling of vacuoles early during infection suggesting intact membranes, but the signal breaks down during recruitment of galectin-8." (PMID 40458442, 2025). "The results showed that 19.93% of Cap(+) strain but only 5.4% of Cap(–) mutant was colocalized with galectin-8 after 3 h of infection." (PMID 38819157, 2024). "Infection with Mm-eccA1::Tn resulted in decreased galectin-8 puncta but substantially more than an Mm-ΔRD1 (26% vs. 7% of wild-type puncta)." (PMID 35271388, 2022). "Because galectin-8 itself is likely ubiquitinated during infection, we predicted that TAX1BP1 would bind to galectin-8 via its UBZ domains." (PMID 34225486, 2021). "In order to elaborate on the role of LGALS8 in the infection process, an siRNA knockdown of LGALS8 with subsequent CFU assay was performed." (PMID 32209695, 2020). "LGALS8 might play a role in altering the balance between Th17 and Th1 cells in the infection of SIV disease." (PMID 27280726, 2016). "However, the roles of fish galectin-8 during pathogen infection require comprehensive studies." (PMID 32676073, 2020). "However, in galectin-8−/− macrophages, but not in galectin-3−/− or galectin-9−/− macrophages, Mtb was not controlled at 24 h postinfection, and bacterial burdens were significantly higher throughout the course of infection." (PMID 34225486, 2021).
bacterial infection (3 papers, 2020 to 2025). "Our data will provide new insights into the function of fish galectin-8 against bacterial infection." (PMID 32676073, 2020). "Although the involvement of galectin-8 in bacterial infection has been recorded in Nile tilapia (Oreochromis niloticus), the exact roles of this molecular during bacterial infection still need to be clarified." (PMID 32676073, 2020). "Galectin-8 has emerged as a key intracellular sensor of membrane damage during bacterial infection." (PMID 40806347, 2025). "The mammalian galectin-8 can detect the bacterial invasion by monitoring the integrity of endosomes and lysosomes, and then activate antibacterial autophagy to protect cells from bacterial infection." (PMID 32676073, 2020). "Furthermore, the involvement of galectin-8 in host defenses against bacterial infection has been well-described in mammals." (PMID 32676073, 2020).